IL6 (interleukin 6)
Diseases named in the same sentence as IL6 in open-access papers (continued):
Sharing a sentence is not in itself a finding about the gene and the disease.
periodontitis (continued). "As an example, the overexpression of miRNA-146a in periodontitis patients was also accompanied by a decrease in the release of pro-inflammatory cytokines (TNF-a, IL-1B, and IL-6), suggesting that the elevation of miRNA-146a regulates pro-inflammatory cytokines through a negative feedback loop." (PMID 36142220, 2022). "This trend was also apparent for IL-6 (participants with severe periodontitis = 1.77; participants with none/mild periodontitis = 1.45) and CRP (severe = 0.13; none/mild = 0.10)." (PMID 36056348, 2022). "On the other hand, correlations were detected between the concentration of IL-6 and either the presence/absence of DM or cancer/periodontitis." (PMID 35804048, 2022). "Despite there being no reports in AP, PBMCs from individuals with periodontitis have also shown a proinflammatory profile with enhanced secretion of interferon-γ, IL-6, IL-12p70, IL-17, and monocyte chemoattractant protein-1 versus their healthy counterparts." (PMID 35300329, 2022). "In the present study, PB levels of IL-6 and the proportion of Treg correlated with the presence and absence of cancer and/or periodontitis in both the univariate and multivariate analyses." (PMID 35804048, 2022). "By contrast, a study in Japan suggested a non-significant reduction in hs-CRP and IL-6 levels after NSPT in patients with periodontitis only." (PMID 36359271, 2022). "Consequently, hsa-miR-203/IL6 and hsa-miR-671-5p/LRIG3 were identified as potential regulatory pathways in periodontitis." (PMID 35397550, 2022). "The concentration of IL-6 was significantly higher in patients with cancer and/or periodontitis than in those with neither cancer nor periodontitis." (PMID 35804048, 2022). "Our previous study found that the expression of GLP-1R was detected on hPDLCs, and LIRA could inhibit the expression of IL-6 and TNF-α on the experimental periodontitis." (PMID 35845316, 2022). "However, periodontitis also triggers systemic inflammation, indicated by an increased level of C-reactive protein (CRP), TNFα, IL-1β, and IL-6 in the serum of patients." (PMID 35874771, 2022). "Similarly, in experimental periodontitis, there is an increase in the circulating levels of CRP, IL-1β, IL-6, and of neutrophils." (PMID 35052857, 2022). "TNF-α, IL-1β, and IL-6 were increased in serum, and VCAM-1 and ICAM-1 were increased in the atherosclerotic plaques of ApoE KO periodontitis mice, accompanied by increased Oil-Red O-stained plaque areas of the aorta after the subgingival injection of LPS for 10 weeks." (PMID 36232471, 2022). "B. lactis HN019 application could markedly decrease the levels of IL-1β and the ratio of RANKL/OPG in rats with periodontitis and metabolic syndrome and could downregulate the expression of TNF-α and IL-6 in rats only with periodontitis." (PMID 35402306, 2022). "Periodontitis-related inflammatory cytokines, such as tumor necrosis factor (TNF) and IL-1β, produced from host cells exposed to the dental biofilm, produce a synergistic effect by increasing IL-6 synthesis resulting in increased Th17 cell activation." (PMID 35628348, 2022). "Therefore, the effects of ginsenosides on IL-6 and TNF-α, the major inflammatory cytokines involved in periodontitis, and the role of HO-1 were evaluated." (PMID 33917440, 2021). "The main finding of the present study was that H2S stimulated the secretion of IFN-γ, IL-6, IL-17, TNF-α, IL-12p40, and IL-12p70, from PBMCs of both periodontitis patients and healthy controls, while the reverse was seen for IL-1Ra, that is, H2S decreased the secretion." (PMID 34408814, 2021). "In addition, a higher basal secretion of IFN-γ, IL-6, IL-12p70, IL-17 and MCP-1 was seen from PBMCs of periodontitis patients compared to healthy controls." (PMID 34408814, 2021). "Moreover, the proinflammatory cytokines, such as IL-1β, IL-6, and TNF-α, have been used as biomarkers to diagnose periodontitis and peri-implantitis." (PMID 34931168, 2021).
periodontitis (continued). "Salivary concentrations of IL-6, and IL-17A were increased in SLE patients with periodontitis." (PMID 33861790, 2021). "The effect of IL-17 and IFN-γ on periodontal gingival tissues and alveolar bone suggests their proresorption roles for periodontitis in vivo, which might partly be explained by their stimulatory effect on IL-1β, TNF-α, and IL-6." (PMID 34395635, 2021). "Additionally, in this study, after the treatment of periodontitis, a decrease in the concentration of interferon gamma (INF-γ), IL-17A, TNF-α, and IL-6 in the blood was demonstrated [49••]." (PMID 33961166, 2021). "Since supernatants obtained from OBMCs of periodontitis patients contain significant levels of pro-inflammatory cytokines such as TNF-α, IL-6 and IL-1β, these cytokines may be inhibitory for the induction of IFN-γ." (PMID 33672708, 2021). "Thus, IL-6, an activator of TGF-β1 activation, was believed to have a protective effect against periodontitis." (PMID 34445604, 2021). "According to our findings, while IL-1β and IL-6 levels had a tendency to be higher in the periodontitis group, the difference with the healthy group was not significant." (PMID 35048079, 2021). "In the present study, the AT1 blockade was shown to reduce the levels of proinflammatory cytokines, such as IL-1ß, IL-6 and TNF-α, but was not able to prevent the bone loss, a hallmark of periodontitis progression." (PMID 34884653, 2021). "AT1-L knockout mice submitted to ligature-induced periodontitis (AT1-L group) and had a significantly lower level of IL-6 in gingival tissue when compared to wild type animals (WT-L) and AT2 knockout mice, both submitted to ligature-induced periodontitis (p < 0.001)." (PMID 34884653, 2021). "There is moderate quality evidence that the IL-6 serum levels are increased in the transplanted individuals with periodontitis in comparison with cases without periodontitis." (PMID 32230707, 2020). "In rats: a ligature-induced (Lig) periodontitis model and Aβ25-35-induced model of Alzheimer’s disease (AD) were established; tumor necrosis factor-α (TNF-α), interleukin 1 (IL-1), interleukin 6 (IL-6), and C-reactive protein levels in the hippocampus and cerebral cortex were detected." (PMID 32614834, 2020). "Transplanted patients with periodontitis have higher serum IL-6 levels than transplanted patients without periodontitis with moderate quality evidence (MD: 2.20 (95% CI: 1.00, 3.39))." (PMID 32230707, 2020). "Increased methylation of the TNF promoter region and decreased IL6 promoter methylation have been observed in the peripheral blood from patients with periodontitis, though the latter observation has not been confirmed in an independent study." (PMID 33256844, 2020). "In addition, it is known that plasma cells produce a variety of pro-osteoclastic factors, such as IL-6, IL-10, Transforming Growth Factor alpha (TGF-α), TGF-β, and matrix metalloproteinases (MMPs), which facilitate the degradation of periodontitis tissues." (PMID 32411181, 2020). "Indirectly, these cells can also induce the amplification of the pro-inflammatory cytokines (IL-1, IL-6, IL-12, IL-17, IL-18, IL-21, TNF-α, and IFN-γ), which are known to be found in periodontitis and to induce osteoclastogenesis via the RANKL–RANK–OPG pathway." (PMID 33143068, 2020). "IL-6 and PGE2 are known as the biomarkers for periodontitis and largely leads to bone resorption." (PMID 33093521, 2020). "Indeed, the acute-phase reactants, interleukin (IL)-6, C-reactive protein (CRP), haptoglobin, fibrinogen, serum amyloid A, and serum amyloid P are elevated in periodontitis patients." (PMID 31293577, 2019). "This enhances the production of diverse inflammatory mediators, including IL-6, CXCL8, and CCL2, which may contribute to the overwhelming immune response and consequently to progression of periodontitis." (PMID 31178663, 2019).
periodontitis (continued). "Since IL-17, IL-6, and IL-33 were found to be significantly elevated in the saliva of SLE/periodontitis subjects compared to periodontitis-only subjects, this systemic imbalance of cytokines may have an impact on periodontal tissues." (PMID 31295952, 2019). "mRNA expression of inflammatory cytokines IL-1β, IL-6, TNF-α and the RANKL/OPG mRNA ratio were increased in periodontitis patients compared with gingival samples of healthy controls (p < 0.05), matching the clinical diagnosis of periodontitis." (PMID 31848404, 2019). "Furthermore, we investigated the effects of Poly I:C on the inflammatory response of hPDLSCs, particularly the gene expression and protein production of IL‐6, IL‐8, and MCP‐1, which are considered to have a crucial impact on periodontitis progression." (PMID 31049957, 2019). "Through the observation of a significant increase in the titers of serum antibodies against P. gingivalis as well as serum IL-6 in OSCC patient samples in the present study, the role of periodontitis and/or P. gingivalis in oral cancer progression has been clinically indicated." (PMID 31167516, 2019). "GFs could secrete IL-6 and CCL2 via activating TLR4 signaling, MAPK, and NF-κB pathways, resulting in the progression of periodontitis." (PMID 31608279, 2019). "Thus, the objective of this study is to explore the relationship between IL-6, TNF-α, and visfatin levels and simvastatin treatment through analyzing the GCFs of patients afflicted with chronic periodontitis and type 2 diabetes." (PMID 30186882, 2018). "IL-6, CXCL-8, and TNF-α may have an important role in the pathogenesis of chronic periodontitis and detection of these cytokines may be beneficial to identify periodontitis patients." (PMID 29670909, 2018). "This was clearly represented through the lack of difference in IL-6 levels among patients with healthy periodontitis (group 1) and diabetic patients afflicted with chronic periodontitis who were undergoing simvastatin treatment (group 4)." (PMID 30186882, 2018). "Mean salivary levels of IL-6 and TNF-α were significantly higher (p = 0.001) in subjects with periodontitis than in healthy subjects: 25.1 (±11.2) vs. 16.3 (±5.0) pg/mL and 29.7 (±17.2) vs. 16.2 (±7.6) pg/mL, approximately 1.5 times and 1.8 times more, respectively." (PMID 29740515, 2018). "Manifesting high levels of cytokines, such as IL-1β, IL-6, and TNF-α, periodontitis has an immunologic profile similar to that of RA and both diseases are associated with elevated concentrations of matrix metalloproteinases (MMPs) and low concentrations of tissue inhibitors of MMP (TIMPs)." (PMID 30211216, 2018). "Experimental models demonstrate that the development of periodontitis in diabetic rats involves a high expression of proinflammatory cytokines (TNF-α, IL-1β, IL-6) and destructive tissue factors as advanced glycation end products (AGEs) without significant changes in commensal oral microbiota." (PMID 30356347, 2018). "The expression of Rorc in CD4+ T cells sorted from cervical lymph nodes was increased during periodontitis in wild-type mice, but not in Il6–/– mice." (PMID 29453398, 2018). "Nevertheless, analysis of for example periodontitis induced by ligatures (either previously incubated with P. gingivalis or not) or oral gavage application of P. gingivalis strain ATCC 33277, revealed elevated serum levels of IL-1β and IL-6." (PMID 28589098, 2017). "On the one hand, the production of IL-6, CXCL8, and CCL2 might promote inflammatory response in periodontitis." (PMID 27504628, 2016). "Cytokines like IL-1α, IL-1β, IL-6, IL-8, and TNF-α have been documented to be involved in immune activation, increased cytotoxic activity, and cytokine-mediated osteoclastic bone resorption in aggressive forms of periodontitis." (PMID 27642305, 2016). "Interleukin-6 correlates with the presence of periodontitis; however, the TNF-α levels do not differ between periodontitis cases and healthy subjects." (PMID 25884025, 2015).
periodontitis (continued). "The overall levels of this cytokine were substantially lower than IL-1ß, and nearly 25% of the healthy/gingivitis groups showed no detectable IL-6 in saliva and only 2/101 periodontitis patients." (PMID 26347856, 2015). "Periodontitis is a common subclinical inflammatory condition characterized by increased production of pro-inflammatory mediators, such as prostaglandin E2 (PGE2), tumor necrosis factor- (TNF-) α, and interleukins IL-1 and IL-6." (PMID 24692844, 2014). "On the other hand, plasma levels of all the interleukins studied (IL-1β, IL-6, IL-11) were not significantly different between study groups (chronic periodontitis, generalized aggressive periodontitis, gingivitis, healthy subjects)." (PMID 25299619, 2014). "It has been suggested that the protein expression levels of IL-6, IL-8 and TNF-α may be clinical parameters of gingival and periodontal inflammatory conditions." (PMID 24137277, 2013). "The levels of IL-6, IL-8 and TNF-α have been observed to be elevated in chronically inflamed gingival tissues, as well as in the gingival crevicular fluid from patients with periodontitis." (PMID 24137277, 2013). "Therefore, in the current study, the levels of IL-6, IL-8 and TNF-α expressed in the human gingival tissues of patients with periodontitis were investigated." (PMID 24137277, 2013). "Elevated IL-6 is higher in recurrent periodontitis cases and increased GCF correlates with gram-negative fimbriae." (PMID 22315682, 2012). "Some studies reported by these authors establish that patients suffering from severe Periodontitis have an increased local production of inflammatory cytokines (IL-1B, TNF-α and IL-6) and a moderate systemic inflammatory response characterized by raised concentrations of CRP, and other mediators." (PMID 28348657, 2011). "Particularly, Periodontitis increases the systemic levels of CRP, IL-6 and leucocytes, which may increase the inflammatory activity in atherosclerotic lesions and in consequence potentially increase the risk of cardiac and cerebrovascular events." (PMID 28348657, 2011). "Non-smokers with moderate periodontitis and periodontally healthy subjects displayed a higher incidence of IL-6 G-genotype than severe periodontitis subjects." (PMID 20170537, 2010). "Periodontitis results in higher systemic levels of CRP and IL-6." (PMID 20407653, 2009). "More recent evidence, however, has indicated that patients with severe periodontitis have increased serum levels of CRP, hyperfibrinogenemia, moderate leukocytosis, as well as increased serum levels of IL-1 and IL-6 when compared with unaffected control populations." (PMID 20407653, 2009). "gingivalis successfully induced periodontitis in mice and led to EndoMT in the hippocampus, characterized by downregulation of ZO-1 and Claudin-5 and upregulation of α-SMA, along with inflammatory activation evidenced by elevated levels of iNOS, IL-1β mRNA, and IL-6 mRNA." (PMID 41908490, 2026). "This could imply that the presence of IL-6 is enhanced in patients with both CKD and periodontitis." (PMID 40452929, 2025). "Reduction in IL-6 post-NSPT suggests a systemic anti-inflammatory effect, which is especially clinically relevant for CKD-P patients as there are potential confounders that could worsen periodontitis amongst CKD patients." (PMID 40452929, 2025). "Measures of periodontitis distance between the cemento‐enamel junction and alveolar bone crest (CEJ–ABC) and number of osteoclasts and psoriasis (epidermal thickness and infiltrate cells (per 0.03mm2)) severity, as well as systemic inflammation (IL‐6, IL‐17A and TNF‐α) were collected." (PMID 40277096, 2025). "The pathogenesis of periodontitis involves a dysbiotic oral microbiota triggering a sustained host immune response, leading to elevated systemic levels of pro-inflammatory cytokines such as tumor necrosis factor-alpha (TNF-α), interleukin-6 (IL-6), and C-reactive protein (CRP)." (PMID 41030757, 2025).
periodontitis (continued). "Furthermore, experimental periodontitis exacerbates inflammation not only by increasing the stromal vascular fraction (SVF) in AT to promote pro-inflammatory cytokine (TNF-α and IL-6) secretion, but also by altering circulating levels of adipokines such as resistin, adiponectin, and leptin." (PMID 41246338, 2025). "This novel model more accurately mimicked clinical UC features, especially the alternating active and remission phases, and revealed that periodontitis may exacerbate UC, likely through elevated inflammatory factors (TNF-α, IL-6) and gut microbiota alterations." (PMID 40462053, 2025). "The host’s susceptibility to systemic disorders increases with periodontitis, largely due to the accumulation of gram-negative bacteria and the elevated levels of inflammatory mediators such as C-reactive protein (CRP) and interleukin-6 (IL-6)." (PMID 40916006, 2025). "Based on our above studies in network pharmacology and molecular docking, we screened and predicted that Kaempferol treatment exhibits a high binding affinity for IL6, CASP3, and MMP9, suggesting that these proteins may be the primary targets of Kaempferol in the treatment of periodontitis." (PMID 40004956, 2025). "Similarly, increased gingival IL-6 and CXCL2 levels were observed in human periodontitis." (PMID 40724937, 2025). "Researchers further conducted in vivo experiments with periodontitis mouse models and reported that F. nucleatum OMV-treated periodontitis model mice presented greater numbers of osteoclasts, more widespread alveolar bone damage, and significant increases in the levels of IL-1β, IL-6, and TNF-α." (PMID 41208888, 2025). "The ability of IL-10 to modulate key pro-inflammatory cytokines such as IL-1β, TNF-α, and IL-6, along with its interplay with IL-17 signaling and its regulatory effects on osteoclast differentiation and ABL, points to its multifaceted role in the pathophysiology of periodontitis." (PMID 41289041, 2025). "Additionally, while there are two studies addressing irisin in the case of periodontitis, none have examined its relationship with visfatin and interleukin-6 in the etiology of periodontal disease (PD)." (PMID 41280712, 2025). "Likewise, patients with periodontitis exhibit elevated IL-6 levels, which significantly decrease following non-surgical treatment." (PMID 40647649, 2025). "However, data yielded by human studies are presently inconsistent, as the circulating levels of CRP, TNF-α, and IL-6 are found to be elevated in T2DM patients with periodontitis in some cases, but not in others." (PMID 39337292, 2024). "Serum levels of IL-6 and IL-8 in periodontitis patients do not seem to be influenced by smoking." (PMID 38627806, 2024). "Reports from a meta-analysis showed that periodontitis therapy lowered systemic inflammation via reductions in both high-sensitivity CRP (hs-CRP) [0.56 mg/L, 95% confidence interval (CI) (−0.88, −0.25), p < 0.001] and IL-6 [0.48 pg/mL, 95% CI (−0.88, −0.08), p = 0.020] levels." (PMID 38667035, 2024). "Further progression of periodontitis did not interfere with the expression of IL-6." (PMID 38541692, 2024). "In addition, lipid peroxidation markers (LPO) and cytokines (TNF-α, IL-6, and IL-10) in the gingival crevicular fluid were significantly elevated in T2DM patients with periodontitis compared to systemically healthy controls with periodontitis." (PMID 39337292, 2024). "Periodontitis patients have significantly elevated levels of LY96, which leads to the formation of LY96-TLR4-CD14 complexes that trigger the myeloid differentiation factor-88 (MyD88) pathway, resulting in TNF-α, IL-6, IL-8, and IL-2 production in the gingival tissue." (PMID 39555084, 2024). "Based on the data evidenced in the group non-diabetic, in which the circulating IL-10 levels were positively correlated with IL-6 and IFN-γ, at baseline, as well as with TNF-α after the treatment ends, we can suggest that a regulatory status was maintained even with the presence of periodontitis." (PMID 39253540, 2024).